TRAF4 (TNF receptor associated factor 4)
Diseases named in the same sentence as TRAF4 in open-access papers (continued):
Sharing a sentence is not in itself a finding about the gene and the disease.
cancer (continued). "Since IGF signaling plays a very important role in various pathological conditions including cancer, regulation of this pathway by TRAF4 presents a potential biomarker and a therapeutic target for intervention." (PMID 33991522, 2021). "The E3 ligase TRAF6-, TRAF4-, and Skp2-mediated K63-linked ubiquitination of AKT is required for AKT activation in human cancer cells." (PMID 32357935, 2020). "Due to the critical role of TRAF4 in tumorigenesis and its druggable enzymatic activity, identification of novel TRAF4 substrates will be helpful for developing new cancer treatment strategies." (PMID 32357935, 2020). "Tumor necrosis factor receptor-associated factor 4 (TRAF4, also known as RING finger protein 83 or RNF83) is emerging as a critical regulator for cancer cell proliferation, survival, and metastasis." (PMID 32357935, 2020). "The present study identifies CHK1 as a novel substrate of TRAF4 that participates in the DDR and pro-survival signaling in multiple cancer cells by orchestrating K63-linked ubiquitination of CHK1." (PMID 32357935, 2020). "As mentioned in other cancers that TRAF4 upregulation promoted the activation of the Akt signaling pathway, we also observed that TRAF4 expression positively correlated with p-Akt level." (PMID 30186853, 2018). "Abnormal TRAF4 expression has been reported in certain cancers, including breast, lung and prostate cancers." (PMID 29343747, 2018). "Available human evidence indicates that gene amplification is the most common TRAF4 genetic alteration in cancers and that TRAF4 expression is ubiquitously elevated in many human cancers." (PMID 30294322, 2018). "Overexpression of KIF11 or TRAF4 eliminated the suppression of carcinoma cell migration by DR6 knockdown." (PMID 30186750, 2018). "On the basis of these structural studies, TRAF4 was identified as a lipid-binding protein that can modulate tight junctions involved in cell migration; abnormal overexpression of TRAF4 can induce carcinomas by affecting cell migration." (PMID 30214450, 2018). "Among the top-scored predicted targets of miR-4443, NCOA1 and TRAF4 have known roles in cell migration and cancer metastasis, and were chosen for validation." (PMID 27842582, 2016). "TRAF4 is located in a region of amplification that is devoid of known oncogenes on chromosome 17q11.2, and is commonly overexpressed in cancer." (PMID 24396457, 2014). "The study indicated that one of the mechanisms responsible for TRAF4 protein overexpression in human cancer was TRAF4 gene amplification." (PMID 24396457, 2014). "Increased TRAF4 gene copy number is one major mechanism responsible for TRAF4 protein overexpression in human cancers." (PMID 23758787, 2013). "While TRAFs are primarily known as regulators of inflammation, antiviral responses, and apoptosis, research on TRAF4 has identified its involvement in development and cancer." (PMID 24311986, 2013). "We propose that TRAF4 has an important function in cancer progression by destabilizing TJs and favoring cell migration." (PMID 24311986, 2013). "TRAF4 protein overexpression is limited to cancer cells and the subcellular localization is consistently cytoplasmic in a large majority of cases." (PMID 23758787, 2013). "Collectively, these data suggest that TRAF4 is not only a marker of human carcinomas, but also a candidate oncogene." (PMID 24212830, 2011). "Since TRAF4 is also observed in the nucleus, most notably in invasive malignant tumors known to be devoid of TJs, a similar shuttling between TJs and nucleus cannot be excluded." (PMID 18953416, 2008). "Additionally, AKT signaling facilitated TRAF4 phosphorylation, aiding nuclear translocation, and making it a potential target for cancer therapy." (PMID 39716976, 2025). "Therefore, extensive efforts have been made to uncover the mechanisms by which TRAF4 regulates cell proliferation, apoptosis, migration, and invasion in various cancer cells." (PMID 36625999, 2023).
cancer (continued). "Furthermore, overexpression of TRAF4 eliminates the inhibition of cancer cell migration via DR6 knockdown." (PMID 36625999, 2023). "TNF receptor-associated factor 4 (TRAF4) represents another RING E3 ligase which has been suggested to promote cancer cell invasiveness and metastasis through non-proteolytic ubiquitylation in cellular models of prostate cancer." (PMID 35136173, 2022). "Besides, TRAF4‐mediated cancer cell proliferation, expression of Cyclin D and C‐myc, as well as the incorporation of BrdU, were accordingly abolished when the TRAFc domain or the Coil‐coil domain was deleted." (PMID 35748027, 2022). "TRAF4 may increase cancer cell viability through the PI3K/AKT/Oct4 pathway to increase cancer cell viability." (PMID 35242717, 2022). "TRAF4 is dynamically localized to the TJs and is overexpressed in cancers." (PMID 35242717, 2022). "TRAF4 up-regulates the protein level of Eg5, which suggests that Eg5 is a downstream protein of TRAF4, and the cancer-promoting effect of TRAF4 may be achieved by regulating the protein level of Eg5." (PMID 35692762, 2022). "The previous studies have pointed out that TRAF4 could activate NF-κB to accelerate cancer development." (PMID 32065218, 2020). "Deep deletion, truncation and fusion of TRAF4 are relatively rare in human cancers." (PMID 30294322, 2018). "The involvement of TRAF4 in the biological behaviour of cancer cells has been reported." (PMID 29343747, 2018). "It has been confirmed that TRAF4 is over-expressed in several different human cancers." (PMID 29499718, 2018). "TRAF4 has been observed to participate in several human cancer developments." (PMID 29499718, 2018). "Notably, TRAF4 is commonly overexpressed in various types of cancers including breast, lung, ovary, colon, and prostate cancer." (PMID 28827764, 2017). "As the dTRAF1 homolog, TRAF4, is amplified in numerous cancers, these findings provide a new mechanism for how the Hedgehog pathway could contribute to tumorigenesis, and, more importantly, provides a new strategy for cancer therapies." (PMID 26974344, 2016). "Moreover, leptin and miR-4443 transfection significantly down-regulated endogenous NCOA1 and TRAF4, both predicted targets of miR-4443 with known roles in cancer metastasis." (PMID 27842582, 2016). "It is interesting that the localization of TRAF4 is altered in cancers." (PMID 25738361, 2015). "Of interest, the subcellular localization of TRAF4 is altered in cancers." (PMID 24311986, 2013). "Importantly, gain of TRAF4 expression and protein mislocalization have been reported in a variety of carcinoma." (PMID 24311986, 2013). "Moreover, TRAF4 has been shown to be overexpressed in numerous human carcinomas and an oncogenic role has been proposed for TRAF4." (PMID 22363515, 2012). "TRAF4 protein overexpression is therefore a common feature of human cancers." (PMID 24212830, 2011). "TRAF4 is overexpressed in many different types of carcinomas." (PMID 24212830, 2011). "Overexpression of MIEN1 and TRAF4 has been reported in various cancers and functionally regulates the PI3K/AKT pathway to promote tumorigenesis, and therefore, this overexpression may contribute to the dysregulated PI3K/AKT signaling pathway observed in refractory MCLs." (PMID 34001881, 2021). "Thus, TRAF4 overexpression has different outcomes in different carcinomas." (PMID 23758787, 2013). "Finally, TRAF4 has also been observed to be overexpressed in various human cancers." (PMID 18953416, 2008). "Functional inference also indicated enrichment of cancer-related orthologs such as LKB1, NFKB1, ITGAV, and TRAF4." (PMID 41356699, 2025). "Specifically, TRAF2, TRAF4, and TRAF7 are generally overexpressed in a pan-cancer context, and high expression levels of these genes are associated with poorer patient prognosis." (PMID 38825674, 2024).
cancer (continued). "The analysis of 33 cancer types revealed that TRAF2, TRAF3, TRAF4, and TRAF7 are predominantly overexpressed, whereas TRAF1, TRAF5, and TRAF6 exhibit lower expression levels." (PMID 38825674, 2024). "This analysis revealed that TRAF1, TRAF2, TRAF3, TRAF4, TRAF6, and TRAF7 exhibit higher expression levels in cancer tissues, whereas TRAF5 is expressed at lower levels in these tissues." (PMID 38825674, 2024). "Mechanistically, knocking down TRAF4, TRAF5, or TRAF6 in retinoic acid-treated cancer cell lines increased the levels of procaspase 9 and induced cell apoptosis." (PMID 37389738, 2023). "Abnormal overexpression and gene amplification of TRAF4 and TRAF6 in human carcinomas have been observed to disrupt cell migration, potentially contributing to cancer development." (PMID 37389738, 2023). "Specifically, TRAF7 exhibited the highest average mRNA level among the TRAF family, followed by TRAF4, while TRAF6 showed the lowest average mRNA level according to the TCGA cancer database." (PMID 37389738, 2023). "Studies have confirmed that TRAF2, TRAF4 and TRAF6 are highly expressed in malignant tumor tissues and play an important role in promoting tumor progression." (PMID 35692762, 2022). "Both TRAF4 and TRAF5 function as activators in the inflammatory process and promote cancer development." (PMID 34983361, 2022). "Collectively, our results enrich the mechanism by which TRAF4 mediates AKT pathway activation, providing insights for AKT pathway research and related cancer treatments." (PMID 36077559, 2022). "However, the signaling pathway and the precise implication of TRAF4 in cancer are still unknown." (PMID 35748027, 2022). "It is likely that TRAF4 and Nedd4 differentially regulate IRS-1 and IRS-2 ubiquitination and subsequent IGF-1 signaling in cancer cells." (PMID 33991522, 2021). "This work significantly expands our understanding of the substrates and functions of TRAF4 in DDR and cancer cell survival." (PMID 32357935, 2020). "In contrast, high expression of TRAF4 enhances CHK1 activation and confers cancer cell chemoresistance, which suggests that TRAF4 functions as an oncogene." (PMID 32357935, 2020). "In the clinical component, we also showed that the combination of ALDOA and TRAF4 or DUSP4 is positively correlated with poor overall survival in a xenograft model and cancer patients through immunohistochemical analyses." (PMID 32188842, 2020). "Gain-of-function alterations (gene amplification and overexpression) are common for TRAF1, TRAF4, TRAF5, and TRAF6 in human cancers, and are also identified for TRAF2 in epithelial cancers." (PMID 30294322, 2018). "Thus, we suggest that regulation of TRAF4 might be a promising strategy for cancer therapy." (PMID 28827764, 2017). "We also demonstrated that inhibiting TRAF4, TRAF5, or TRAF6 could suppress cancer cell proliferation, highlighting the critical oncogenic role of TRAFs in carcinogenesis." (PMID 37389738, 2023). "TRAF4 has been reported as a positive regulator for cell growth/proliferation pathways (AKT, ERK1/2, and ERK5) induced by EGF, TGF-β, and IL-17A signaling, contributing to the proliferation and migration of cancer cells." (PMID 37607012, 2023). "Overexpression and gene amplification of TRAF4 and TRAF6 have been reported in human carcinomas." (PMID 23758787, 2013). "In contrast, TRAF4 is never localized at the plasma membrane of poorly-differentiated invasive carcinomas devoid of correct TJs, but is observed in the cytoplasm and/or nucleus of the cancer cells." (PMID 18953416, 2008). "Finally, for DMRs whose associated genes had increased expression upon treatment with FQI1, we observed enrichment of GO terms for pathways in cancer (e.g. PIAS4, SMAD3, TRAF4, MAP2K1) and RNA transport (e.g. NUP188, EIF3A, NUP35, RAN) in both hyper and hypomethylated DMRs." (PMID 27845898, 2016). "TRAF4 overexpression is always observed in cancer cells and never in stromal cells." (PMID 24212830, 2011).
cancer (continued). "Interestingly, aggressive malignant tumors never exhibit membrane TRAF4 staining." (PMID 18953416, 2008).
tumor (45 papers, 2013 to 2025). "The in vivo tumor growth was delayed in the TRAF4-deficient CNE2 tumors after IR (2 Gy) treatment three times (Total 6 Gy) compared with that in TRAF4-proficient CNE2 tumors." (PMID 38164179, 2024). "We also demonstrate a TRAF4-dependent association between tumor cell stemness, CD44v expression, and increased synthesis of hyaluronan." (PMID 33804427, 2021). "Tumor necrosis factor receptor-associated factor 4 (TRAF4) has been shown to play emerging roles in tumor metastasis, development, and chemo-resistance." (PMID 32087604, 2020). "A Kaplan–Meier analysis demonstrated that the miR-29a/b/c and TRAF4 levels were closely associated with patient survival even in patients with the same tumor grade and identical IDH gene status." (PMID 30348972, 2018). "Notably, nuclear TRAF4 elevated the expression of biomarkers associated with tumor dormancy and stemness, while cytoplasmic TRAF4 had a weaker effect." (PMID 39716976, 2025). "Therefore, the results of this study not only set up a clear clinical association of TRAF4, but also elucidate an abnormal signaling pathway for tumor cell proliferation." (PMID 35748027, 2022). "However, the crucial role of TRAF4 in radiation resistance and its underlying mechanism in human tumor, including OSCC, remains elusive." (PMID 36535926, 2022). "These core genes—TRAF4, UBE2L3, FBXO45, UBE2L6, FBXL14, SKP2, CHAF1B, and WDR77—have been implicated in tumor progression in previous studies." (PMID 40990020, 2025). "TRAF4, an E3 ubiquitin ligase, is frequently overexpressed in tumors, and its nuclear localization is correlated to tumor grade and stemness." (PMID 39716976, 2025). "This increased nuclear translocation of TRAF4 significantly facilitated tumor sphere formation and cell invasion in HCT116, MDA‐MB‐231, and U‐87 MG cells." (PMID 39716976, 2025). "We also confirmed that enhanced nuclear translocation of TRAF4 increased the frequency of tumor spheres through an in vitro limiting dilution assay." (PMID 39716976, 2025). "To investigate how nuclear TRAF4 promotes tumor stemness and dormancy, we conducted RNA sequencing on U87‐MG cells overexpressing NLS‐TRAF4." (PMID 39716976, 2025). "The IL‐8 neutralizing antibody effectively inhibited tumor cell invasion induced by TRAF4 nuclear accumulation." (PMID 39716976, 2025). "Consistently, biomarkers associated with cell dormancy as well as stemness were upregulated in tumor cells expressing high levels of TRAF4; however, their expression, including DEC2, SOX9, NR2F1, and P27, declined in cells expressingTRAFA‐P12A." (PMID 39716976, 2025). "When cells reach a metastatic lesion, they receive signals from IL‐8 produced by stromal cells in that lesion, which promotes the entry of TRAF4 into the nucleus and initiates the process of tumor dormancy." (PMID 39716976, 2025). "In tumor cells, TRAF4‐P12A also inhibited TRAF4 nuclear accumulation compared with wild‐type TRAF4 (wt‐TRAF4)." (PMID 39716976, 2025). "We verified that TRAF4 regulated IL‐8 at both RNA and secretory levels after overexpression of NLS‐TRAF4 in tumor cells." (PMID 39716976, 2025). "Our results indicated that the addition of NLS further enhanced TRAF4 nuclear accumulation in tumor cells, compared with wt‐TRAF4." (PMID 39716976, 2025). "The results demonstrated a marked increase in nuclear TRAF4 expression within these tumor tissues compared with their corresponding normal counterparts." (PMID 39716976, 2025). "This interaction subsequently led to an enhancement of the promoter activity of interleukin‐8 (IL‐8), which is identified as a mediator of nuclear TRAF4‐induced tumor dormancy." (PMID 39716976, 2025). "Compared with the TRAF4‐KO group, the restoration of nuclear TRAF4 remarkably promoted tumor sphere formation and cell invasion in HCT116, MDA‐MB‐231, and U‐87 MG cells." (PMID 39716976, 2025).
tumor (continued). "Compared with non‐tumor cells, nuclear TRAF4 levels were significantly elevated in multiple tumor cell lines, suggesting that the nuclear localization of TRAF4 is a general phenomenon." (PMID 39716976, 2025). "Although the recovery of cytoplasmic TRAF4 also boosted tumor stemness, its effect was less pronounced than that of nuclear TRAF4." (PMID 39716976, 2025). "The in vitro limiting dilution assay further demonstrated that reduced nuclear translocation of TRAF4 led to a decreased frequency of tumor spheres." (PMID 39716976, 2025). "To identify the upstream signaling that triggers the nuclear translocation of TRAF4, we stimulated tumor cells using several cytokines found in the tumor microenvironment." (PMID 39716976, 2025). "Subsequently, we stably expressed NLS‐TRAF4 and TRAF4‐P12A in the TRAF4‐KO tumor cells to restore the nuclear or cytoplasmic expression of TRAF4." (PMID 39716976, 2025). "Nuclear TRAF4 served as an independent indicator of tumor aggressiveness and differentiation, acting as a poor prognostic factor." (PMID 39716976, 2025). "The data indicated that tumor volume, mass, and weight were significantly reduced in TRAF4-depleted CNE2 tumors." (PMID 38164179, 2024). "The expression of TRAF4, p-Akt, and survivin proteins was a positive correlation in NPC tumor tissues expressing low or high TRAF4." (PMID 38164179, 2024). "The data indicated that TRAF4 was overexpressed in NPC tissues when compared to the adjacent non-tumor tissues." (PMID 38164179, 2024). "The xenograft tumor model was further conducted to validate the effect of TRAF4 on radioresistance in vivo." (PMID 38164179, 2024). "Our data revealed that TRAF4 KO markedly increased the number of tumor colonies and shortened the colon length induced by AOM/DSS inflammation‐induced CRC, but had little effect on mouse body weight." (PMID 38229144, 2024). "Knockdown of TRAF4 resensitized CNE2R cells to radiotherapy, as the tumor volume, tumor mass, and tumor weight were reduced significantly when compared to that of the TRAF4 proficient CNE2R tumors." (PMID 38164179, 2024). "We then generated the xenograft tumors using HT29R cells and found that tumors from TRAF4-knockout cells combined with irradiation exhibited the lowest tumor growth rate." (PMID 36765039, 2023). "Compared with those in paired adjacent non-tumor tissues, the TRAF4, c-Jun and Bcl-xL protein levels were significantly upregulated." (PMID 36765039, 2023). "Our investigation shows that TRAF6 as well as TRAF4 genes are highly amplified in samples from metastatic breast cancer patients (TRAF6: 9.3% and TRAF4: 27.8%) when compared primary tumours (TRAF6: 7.2% and TRAF4: 21.7%)." (PMID 36944688, 2023). "Follow-up studies have found that TRAF4 is overexpressed in a variety of tumor tissues and plays an important role in promoting tumorigenesis and regulating tumor cell proliferation, apoptosis, migration, invasion and other biological behaviors." (PMID 35692762, 2022). "Through immunohistochemical experiments, we verified that the TRAF4 expression in subcutaneous tumor tissue decreased, and the SETDB1 expression were also decreased in accordance with TRAF4, which were consistent with previous cell experiments." (PMID 36077559, 2022). "The study of TRAF4 can identify new targets suitable for tumor therapy and lay the foundation for developing new drugs and tumor drug resistance research." (PMID 35242717, 2022). "Compared with those of the Ctrl group, tumor growth, tumor mass, tumor weight and tumor cell proliferation were significantly decreased in the xenograft tumors derived from TRAF4 knockout." (PMID 36535926, 2022). "In the TRAF4-knockout xenograft tumors, the introduction of JOSD1 markedly attenuated the antitumor effects of blocking TRAF4 even in the presence of IR, as demonstrated by the tumor growth rate, tumor mass and tumor weight, which significantly increased." (PMID 36535926, 2022).